PWAR5 (Prader Willi/Angelman region RNA 5)
Synonyms: PAR5; PAR-5; D15S226E
Gene: Gene on chromosome 15 (24,985,053 to 24,988,232, forward strand). Ensembl gene ENSG00000279192.
Diseases named in the same sentence as PWAR5 in open-access papers:
PWAR5 is named in the same sentence as 13 diseases in open-access papers, as found by Europe PMC text mining. Sharing a sentence is not in itself a finding about the gene and the disease. The quoted sentences say what the papers report.
myocardial infarction (1 paper, 2020). Gross necrosis of the myocardium, as a result of interruption of the blood supply to the area, as in coronary thrombosis. "Here, patients with high expression levels of KIAA0495 showed shorter survival, while patients with low expression levels of PART1, MGC21881, myocardial infarction-associated transcript (MIAT), growth arrest-specific 5 (GAS5), and Prader Willi/Angelman region RNA 5 (PAR5) showed prolonged survival." (PMID 32650527, 2020).
tumor (10 papers, 2014 to 2023). "Among these dysregulated lncRNAs, H19 expression increased with the tumor malignancy grade, whereas expression of Prader Willi/Angelman region RNA 5 (PAR5) and RFPL1 antisense 1 (RFPL1S) decreased with increasing tumor grade." (PMID 28187439, 2017).
cancer (6 papers, 2020 to 2024). A tumor composed of atypical neoplastic, often pleomorphic cells that invade other tissues. "The second candidate, PAR5/PWAR5 (Prader Willi/Angelman region RNA 5), has also been associated with other carcinomas, and acts by reducing EZH2 activity, although its potential role in HCC awaits validation." (PMID 32214045, 2020).
PWAR5 also shares sentences with these, for which no sentence is quoted: glioma (6 papers); glioblastoma multiforme (5); anaplastic thyroid carcinomas (3); hepatocellular carcinoma (2); thyroid cancer (2); bladder cancer (1); Bladder Urothelial Cancer (1); cystic fibrosis (1); prostate carcinoma (1); thyroid (1).